FOXP3 (forkhead box P3)
Diseases named in the same sentence as FOXP3 in open-access papers (continued):
Sharing a sentence is not in itself a finding about the gene and the disease.
lung carcinoma (continued). "The development of multiple therapies that deplete Foxp3+ cells at different stages of K-Ras induced tumorigenesis might eventually provide new options for lung cancer treatment and prevention." (PMID 19330036, 2009). "Research suggests that combining cryoablation with a traditional Chinese lung-nourishing formula may decrease CD4+ CD25+ Foxp3+ Treg cell proportions in the spleen and reduce Foxp3 expression in tumor tissues, thereby inhibiting Lewis lung cancer proliferation." (PMID 41438510, 2025). "Targeting FOXP3 by the PRMT5 inhibitor could be promising in lung cancer treatment." (PMID 38898200, 2024). "Therefore, targeting FOXP3 regulatory T cells may hold promise as a therapeutic approach, and assessing their levels could provide valuable prognostic information for lung cancer patients." (PMID 38674427, 2024). "A former study has noticed increased Treg cells and Foxp3 expression, decreased Th17 cells and RORγt expression and Th17/Treg ratio, and negative correlation of Th17/Treg to cancer stages in the peripheral blood of elderly lung cancer patients, compared with healthy people." (PMID 36434505, 2022). "However, we found that such Foxp3+ T cells are located in lung cancer tissue of NSCLC patients." (PMID 35514957, 2022). "Therefore, other therapeutic approaches may need to be developed to selectively deplete Foxp3+ cells in advanced K-Ras driven lung cancers." (PMID 19330036, 2009). "EVs also increased PD-1, CTLA-4, FOXP3, TNF-α, IL-12, and INF-γ mRNA in lung cancer patients’ immune cells." (PMID 40725070, 2025). "CD8+ T cells alter the lung cancer microenvironment and facilitate the migration of CD4+Foxp3+ Tregs to the tumor bed." (PMID 40553564, 2025). "The upregulation of FOXP3 and GLI1 increased the expression lung cancer stem cell markers (e.g., ALDH1A1 and OCT4) and the formation of tumor spheres." (PMID 38674427, 2024). "The authors pinpointed intratumoral CD68-positive macrophages, M1 macrophages and intrastromal CD4+ cells, CD4+ FOXP3- cells, CD8+ cells and PD-L1+ cells to be the most robust prognostic biomarkers for DFS in lung cancer." (PMID 38674427, 2024). "For validation, formalin-fixed tissues from 375 lung ADC, 118 lung squamous cell carcinoma (SqCC), 338 colon ADC, and 78 lung cancer patients treated with anti-PD-1/PD-L1 immunotherapy were immunostained for HK2, CD8, and FOXP3." (PMID 36320008, 2022). "An increased FoxP3/CD8 ratio was a predictor of reduced survival in this study as well as in cervical cancer, esophageal cancer and lung cancer." (PMID 35140715, 2022). "Examining lung cancers, we showed that a high density of CD8 cytotoxic T cells and Foxp3 immunosuppressive regulatory T cells in the tumor microenvironment correlated with a cyto-nuclear expression of ZO-1." (PMID 34938731, 2021). "In patients with lung cancer, CD8+CD28− T cells have elevated Foxp3 expression and show immunomodulatory effects." (PMID 34259422, 2021). "Then, we employed GEPIA program to analyze the expression of these 16 TFs using TCGA data, and found that only FOXP3 and STAT1 were significantly highly expressed in lung cancer specimens." (PMID 32396871, 2020). "Then, we searched “GEPIA”, finding that FOXP3 and STAT1 levels were distinctly upregulated in lung cancer." (PMID 32396871, 2020). "We prepared single cell suspensions from EBUS-TBNA samples of mediastinal lymph nodes from patients with sarcoidosis or lung cancer and analyzed surface markers (CD3, CD4, CD8, CD19, CD25) and FoxP3 expression in the resultant lymphocytes using flow cytometry." (PMID 30452447, 2018). "Among the six subgroups, the elderly lung cancer patients exhibited the highest levels of both CD4+CD25+FOXP3+ Treg (11.81 ± 2.40%) and FOXP3 mRNA (3.14 ± 1.30)." (PMID 28253320, 2017). "The increased proportion of Tregs, high expression of Foxp3 and CTLA-4 on tumor infiltrating and peripheral blood lymphocytes have been observed in lung cancer." (PMID 27866241, 2017).
lung carcinoma (continued). "The levels of CD4+CD25+FOXP3+/CD4+ T cells and FOXP3 mRNA were significantly higher in lung cancer patients than in healthy controls (t = 7.16, P < 0.01 and t = 3.65, P < 0.01, respectively)." (PMID 28253320, 2017). "Most importantly, we observed that DC-based HHP lung cancer vaccine stimulates proliferation and IFN-γ production in CD8+ and CD4+ T cells and lowers the numbers of CD4+CD25+Foxp3+ T regulatory cells in vitro." (PMID 28187172, 2017). "Tumor samples from three lung cancer patients were analysed by flow cytometry, staining for CD19, CD3, CD4, CD8, Foxp3, TNFR2, GITR and OX40." (PMID 27626702, 2016). "In lung cancer, CD4+ T cells present intracellular C3 cleavage by cathepsin and C3a signaling inhibits the production of multiple cytokines by CD4+ T cells, independently of FOXP3+ Tregs." (PMID 40370471, 2025). "The number of Foxp3+ Tregs in lung cancer tissue was increased compared to non-cancer tissue, particularly in the group of TSLP+ cancers." (PMID 40873585, 2025). "However, a related study showed that inhibiting USP7 increased the expression of PD-L1 in lung cancer cells, and higher levels of USP7 promoted tumor growth by altering the immunosuppressive characteristics of Forkhead box protein P3 (Foxp3)+ Treg." (PMID 39748950, 2024). "Jiang etal’s study found a negative correlation between Foxp3+Tregs cell infiltration in the tumor matrix and lung cancer prognosis." (PMID 37712056, 2023). "A previous study found increased Treg cells abd Foxp3 expression, decreased Th17 cells and RORγt expression, diminished Th17/Treg ratio and negative correlation with cancer stages in elderly lung cancer patients." (PMID 36434505, 2022). "Cancers with high tumor-infiltrating lymphocytes (e.g., lung cancers) had high expression of immune-oncology markers, such as PD-L1, TIM3, FOXP3, PD-1, CTLA4, and LAG3 in TMA EdgeSeq and TCGA RNA-seq; this was also observed in normal hematopoietic tissues with TMA EdgeSeq." (PMID 36137139, 2022). "Immunohistochemistry results showed that FOXP3 was mainly expressed in Tregs, but not in lung cancer tissues." (PMID 36550816, 2022). "Overall, understanding the prognostic significance of FOXP3 in NSCLC tumors and its involvement in therapy resistance may help to develop more effective targeted therapeutic strategies to improve clinical outcomes in patients with lung cancer." (PMID 38674427, 2024). "Several studies have also reported that the CD4+/CD25(high)/FoxP3+/CD127- Tregs content is related to the prognosis of lung cancer patients, and the number of Tregs in the bronchoalveolar lavage fluid of patients with lung cancer has been found to be higher than that of patients with benign lesions." (PMID 38475858, 2024). "As IL-10 and TGF-beta expressing T cells are known to play a crucial role for inducing Foxp3+ T regulatory cells and controlling immune responses in NSCLC, these results suggest that IL-9 plays an important role in regulating immune responses in lung cancer in vivo." (PMID 35514957, 2022). "IRF1 is downregulated in lung cancer, IPF and PAH datasets, probably because it represses the expression of genes involved in anti-proliferative response, such as BIRC5/survivin, CCNB1, CCNE1, CDK1, CDK2 and CDK4 and in immune response, such as FOXP3, IL4, ANXA2 and TLR4." (PMID 31867044, 2019). "Foxp3 is a transcription factor that is upregulated in TILs and tumor cells and coveys a negative prognostic factor in the lung cancer and maybe a future target for resistant tumors." (PMID 28434399, 2017). "The proportion of CD4+/CD25high/Foxp3+/CD127- Tregs determined by flow cytometry and the proportion of Tregs with expression of (in)CTLA-4 were significantly elevated in the BALF harvested from the lung affected by lung cancer when compared with the last two compartments." (PMID 27866241, 2017).
lung carcinoma (continued). "The lower proportion of CD8+ cells and higher Foxp3+/CD8+ ratio in metastatic when compared with nonmetastatic LNs in adenocarcinoma may indicate a particular biology of this type of lung cancer." (PMID 28831395, 2017). "However, more recently lung cancer studies have shown that CD27 expression on human CD4+CD25+ Tregs positively correlates with their suppressive activity in vitro and the expression of FOXP3." (PMID 25951351, 2015). "Blood-derived γδTc stimulated with anti-γδ TCR mAb for 14 days in vitro expressed only low levels of FoxP3, regardless of whether from healthy donors or lung cancer patients." (PMID 25477885, 2014). "In addition, Foxp3 protein was not expressed in human lung cancer cell lines or cell lines derived from murine lung tumors." (PMID 19330036, 2009). "Therefore, the elevated FOXP3+ expression in TILs might be a negative predictive value for (programmed death 1) PD-1 inhibitor therapy in lung cancer." (PMID 38674427, 2024). "The proportion of CD4+/CD3+/CD25+/FoxP3+ CD4+ Treg cells and CD8+/CD3+/CD25+/FoxP3+ regulatory CD8+ Treg cells were significantly elevated in all the lung cancer patients before surgery, but not in the RFC group after surgery." (PMID 37238744, 2023). "In a preclinical model of mice bearing lung carcinoma, paclitaxel has been demonstrated to selectively inhibit CD4+FOXP3+ Treg cells, but not other CD4+FOXP3- T helper cells." (PMID 33276524, 2020). "Furthermore, phosphorylation levels of SMAD3 in CD3, CD8, Foxp3, and CD68 cells in non-small cell lung cancer negatively impact the overall and partial disease-free survival in lung cancer patients, independent of histological subtype." (PMID 37685308, 2023).
enteropathy (111 papers, 2006 to 2026). "Variants in FOXP3 are known to be associated with several diseases, including immunodysregulation, polyendocrinopathy, enteropathy, and hydrops fetalis." (PMID 40625169, 2025). "The discovery of Tregs and their reliance on Foxp3 was initially highlighted by studies of the scurfy mouse and immune dysregulation, polyendocrinopathy, enteropathy, X-linked (IPEX) syndrome in humans, both caused by mutations in the Foxp3 gene." (PMID 41459507, 2025). "In the third family, two deceased fetuses diagnosed with CNM had a hemizygous pathogenic variant in the FOXP3 gene linked to a syndrome with immunodysregulation, polyendocrinopathy, and enteropathy." (PMID 38982518, 2024). "Immune dysregulation, polyendocrinopathy, enteropathy, X-linked (IPEX) syndrome is characterized by enteropathy, severe dermatitis, and autoimmune endocrinopathies due to hemizygous mutation in the FOXP3 gene." (PMID 38535602, 2024). "Recent research has shown that immune dysregulation, polyendocrinopathy, enteropathy, and X-linked syndrome are caused by mutations in FOXP3, indicating that this is the master gene of Tregs." (PMID 35358193, 2022). "Mutations in the FOXP3 gene lead to a systemic disease called immune dysregulation, polyendocrinopathy, and enteropathy, an X-linked syndrome (IPEX) characterized by the triad of early-onset intractable diarrhea, type 1 diabetes, and eczema." (PMID 35479070, 2022). "Immune dysregulation, polyendocrinopathy, and enteropathy (IPEX) is caused by mutations in the FOXP3 gene, a master regulator of the development and function of Tregs." (PMID 30565237, 2019). "Interleukin (IL)-4 production by CD4+ T cells was measured as a causative factor of enteropathy, and anti-IL-4 antibody was used to reveal the role of Foxp3+ OVA-specific Tregs (aiTreg) in this process." (PMID 28234975, 2017). "Diarrhea is one of the manifestations of IPEX (immune dysregulation, polyendocrinopathy, enteropathy, and X-linked syndrome), which is caused by FOXP3 mutation." (PMID 26839896, 2016). "On the other hand, disruption of FoxP3+ Treg is known to lead to dysregulation of allergic immune responses, as evidenced to Foxp3 mutations in scurfy mice and in humans (i.e. immune dysfunction, polyendocrinopathy, enteropathy, X-linked syndrome)." (PMID 24086630, 2013). "The role of FoxP3 in maintaining self-tolerance was first identified in scurfy mice, and then in humans with immunodysregulation, polyendocrinopathy, enteropathy, X-linked (IPEX) syndrome, both of which have a FoxP3 mutation as the underlying genetic defect." (PMID 22754651, 2012). "FOXP3 mutations (X-linked) are responsible for neonatal diabetes syndrome associated with X-linked immune dysregulation and enteropathy." (PMID 21050479, 2010). "Tregs express FOXP3 as the most specific marker, and it has been shown that FOXP3-deficient individuals have severe autoimmune/autoinflammatory conditions, like immune dysregulation, polyendocrinopathy, enteropathy, and X-linked syndrome (IPEX)." (PMID 39936954, 2025). "Similarly, pathogenic FOXP3 mutations in humans lead to immunodysregulation, polyendocrinopathy, enteropathy, and X-linked (IPEX) syndrome, which are characterized by systemic autoimmunity that typically begins in the first year of life." (PMID 34737751, 2021). "In addition, mutations in Foxp3 have been shown to induce immunodysregulation, polyendocrinopathy, enteropathy, and X-linked syndrome." (PMID 27802847, 2016). "In general, severe enteropathy develops in humans deficient in Foxp3 expression and mice deficient in Tregs, and Foxp3+ Tregs of psoriasis patients are susceptible to differentiation into IL-17A that has a highly pathogenic role in skin inflammation and the development of psoriatic plaques." (PMID 27802847, 2016). "However, patients with mutations affecting the Foxp3 gene develop immune dysregulation, polyendocrinopathy, enteropathy, and X-linked syndrome (IPEX)." (PMID 22849659, 2012).
enteropathy (continued). "Mutations in the human FOXP3 gene causes the disease Immune dysregulation, Polyendocrinopathy, Enteropathy, X-linked syndrome (IPEX), and the Foxp3 mutant Scurfy mouse model displays a similar pathology involving dysregulated CD4+ T cell infiltration and activation." (PMID 18286169, 2008). "FOXP3 was initially identified as the gene responsible for an X-linked recessive inflammatory disease in scurfy mutant mice, as well as fatal autoimmune/inflammatory disease, immune dysregulation, polyendocrinopathy, enteropathy, or X-linked syndrome in humans." (PMID 38550796, 2024). "Identifying increased %TSDR/CD4 in patients with novel FOXP3 mutations presenting with isolated diabetes facilitates diagnosis and could offer an opportunity to monitor patients and begin immune modulatory treatment before onset of severe enteropathy." (PMID 36600150, 2023). "However, FoxP3 holds a pivotal role to regulatory T cell function, as evidenced by the X-Linked syndrome of immune dysregulation, polyendocrinopathy, and enteropathy (IPEX) caused by a mutation in the FoxP3 gene leading to large amounts of polyclonal T-cell activation and tissue infiltration." (PMID 36016949, 2022). "Primary defects of FOXP3 and CD25, which directly affect Treg cell development and function, cause IPEX (Immune dysregulation, poly endocrinopathy, enteropathy, X-linked) and IPEX-like disease, respectively." (PMID 40804844, 2025). "The anti-inflammatory roles of Treg cells are most obviously seen in subjects with the immune dysregulation, polyendocrinopathy, enteropathy, or X-linked (IPEX) syndrome caused by mutations in the transcription factor forkhead box protein P3 (FoxP3)." (PMID 36010663, 2022). "Mutation of the FOXP3 gene leads to immunodysregulation, polyendocrinopathy, enteropathy, X-linked (IPEX) syndrome with dermatitis, enteropathy, diabetes, thyroid disorders, and anemia." (PMID 35743361, 2022). "Human mutations in the FOXP3 gene cause an X-linked syndrome (IPEX) characterized by immune dysregulation, polyendocrinopathy, and enteropathy." (PMID 31162141, 2019). "We present the case of a boy with metaplastic atrophic gastritis in whom immune dysregulation, polyendocrinopathy, enteropathy, X-linked(IPEX) syndrome was confirmed by FOXP3 gene mutation." (PMID 29907148, 2018). "Mutations in Foxp3 lead to the X-linked immunodeficiency syndrome IPEX in humans (immune dysregulation, polyendocrinopathy, enteropathy, X-linked syndrome)." (PMID 16551363, 2006). "The involvement of Tregs was initially suggested by the analysis of immunodysregulation, polyendocrinopathy, enteropathy, X-linked (IPEX) patients who suffer from FOXP3 deficiency and showed elevated frequencies of circulating autoreactive mature naive B cells in the absence of functional Tregs." (PMID 41026527, 2025). "Forkhead Box P3 (FOXP3) is crucial for sustaining the proper function and differentiation of regulatory T cells in which the variant of FOXP3 leads to immune dysregulation, polyendocrinopathy, enteropathy, and X-linked (IPEX) syndrome." (PMID 39859044, 2025). "In contrast, none of the patients with enteropathy without FOXP3 mutations (i.e. IPEX-like or PID), patients with T1D or celiac disease were positive for either HAA or VAA." (PMID 24250806, 2013). "Monogenetic loss-of-function mutation of an X-linked gene called Foxp3 (forkhead box p3) was found to be accountable for multifocal lymphoproliferation autoimmunity syndrome in scurfy mice and IPEX (immunodysregulation, polyendocrinopathy, and enteropathy, X-linked) human patients." (PMID 37217798, 2023). "Foxp3 mutation in humans results in a similar autoimmune syndrome termed IPEX (immunodysregulation, polyendocrinopathy, enteropathy and X‐linked syndrome) with symptoms of insulin‐dependent diabetes, thyroiditis, enteropathy, infections, endocrinopathy and eczema." (PMID 32729205, 2020).
enteropathy (continued). "Mutations in the FOXP3 gene have deleterious consequences, leading to autoimmune phenotypes in both mice (scurfy mice) and humans (IPEX—immunodysregulation, polyendocrinopathy, enteropathy, X-linked syndrome), highlighting the crucial role of Foxp3 for Treg function." (PMID 31836704, 2019). "Several SNPs of Foxp3 that occur at high frequencies in the general population have been widely investigated in common multifactorial human diseases, such as AITD, immunodysregulation, polyendocrinopathy, enteropathy, X‐linked (IPEX) syndrome, and type 1 diabetes." (PMID 30710380, 2019). "Recently, Foxp3- CD4+CD25+CD127- iTreg with appreciable suppressive activity on effector T cell proliferation, although less than that displayed by Treg cells from healthy controls, were demonstrated in patients with immune dysregulation, polyendocrinopathy, enteropathy, X-linked (IPEX) syndrome." (PMID 22905732, 2012). "In the enteropathy model, the changes in CD4+ T cells were also accompanied by an increase in CD4+/Foxp3+ (Tregs) cells, which suggests the development of a counter-regulatory response, as previously reported." (PMID 22348021, 2012). "The role of Tregs in establishment of systemic tolerance is well described, in part due to the inborn error of immunity resulting from lack of functional FOXP3, known as IPEX (Immune dysregulation, Polyendocrinopathy, Enteropathy, and X-linked syndrome)." (PMID 40280180, 2025). "For instance, patients with FOXP3, IL2RA, and LRBA PNDM may present similar extrapancreatic features (eg, enteropathies, hypothyroidism)." (PMID 38408297, 2024). "In mice, conditional deletion of Foxp3 in CD4+ T cells leads to fatally lymphoproliferative autoimmunity, which includes high IgE levels, enteropathy, type 1 diabetes and failure to thrive, while ectopic expression of Foxp3 can re-program conventional CD4+ T cells as anti-inflammatory Treg cells." (PMID 31681337, 2019).